FGFR1 (fibroblast growth factor receptor 1)
Diseases named in the same sentence as FGFR1 in open-access papers (continued):
Sharing a sentence is not in itself a finding about the gene and the disease.
leukemia (45 papers, 2010 to 2025). A malignant (clonal) hematologic disorder, involving hematopoietic stem cells and characterized by the presence of primitive or atypical myeloid or lymphoid cells in the bone marrow and the blood. "The identification of IGF1R and FGFR1 as novel components of TSLP/CRLF2 signaling enhances our understanding of the molecular mechanisms that underlie TSLP-mediated leukemia proliferation." (PMID 40787610, 2025). "Here, we identified that the loss of FGFR3 reprograms MLL-AF9 (MA)-driven murine AML cells into weakly pathogenic CD117-positive leukemia stem-like cells by activating the FGFR1-ERG signaling pathway." (PMID 33584313, 2020). "The FGFR1 Oncogene Partner (FOP) was first identified as the fibroblast growth factor receptor 1 (FGFR1) oncogene fusion partner in the leukemia-associated chromosomal translocation." (PMID 33304902, 2020). "FOP (FGFR1 oncogene partner) was first described as the fusion partner of FGFR1 in a leukemia-associated chromosomal translocation." (PMID 23554904, 2013). "This behavior is similar to what is seen in chronic myeloid leukemia blast crisis or in leukemias/lymphomas associated with FGFR1 rearrangement." (PMID 23710385, 2013). "In addition, elucidation of molecular mechanisms underlying FGFR1-driven leukemias and lymphomas also provides new targets for combined treatment as another option to bypass the FGFR1 inhibitor resistance and improve patient outcome." (PMID 34734169, 2021). "The observation that increased FGFR1 activity, whether through overexpression or upregulation through chromosome translocations is implicated with leukemia development, led us to investigate whether FGFR overexpression is a frequent event in de novo AML." (PMID 27391347, 2016). "In this report we describe the case of a patient with a ZMYM2:FGFR1 fusion-driven leukemia who was successfully treated with FGFR kinase-targeting inhibitors." (PMID 40881645, 2025). "A literature review conducted on the treatment of leukemia with the BCR::FGFR1 translocation underscores the importance and effectiveness of allogeneic hematopoietic SCT as a primary therapy to achieve molecular remission in acute leukemia." (PMID 41180818, 2025). "Inhibiting the fibroblast growth factor 2 and fibroblast growth factor receptor 1 (FGF2-FGFR1) signaling pathway reduced exosome secretion and sensitized leukemia cells to TKIs, indicating a potential therapeutic approach to counteract drug resistance." (PMID 41502528, 2025). "As described in the literature, the BCR::FGFR1 translocation has been observed in cases with mixed phenotype leukemia." (PMID 41180818, 2025). "Leukemias driven by activated, chimeric FGFR1 kinases typically progress to AML which have poor prognosis." (PMID 38730491, 2024). "Common mutations found in leukemia patients, such as ABL1, FGFR1, KRAS, MET, NOTCH1, and PTPN11, were also found among our patient population, although not universally." (PMID 37092520, 2023). "In spite of this, we determined that it is important to make inquiry about the FGFR1 status of the leukemia cells in this case." (PMID 38098111, 2023). "In a limited preclinical study, we have shown that leukemias with upregulation of FGFR1 are sensitive to a wide variety of FGFR1 inhibitors." (PMID 35906694, 2022). "Activation of FGF2/FGFR1 signaling in bone marrow stromal cells promoted the secretion of FGF2/ FGFR1-laden exosomes, which were internalized by leukemia cells and contributed to their resistance to tyrosine kinase inhibitors." (PMID 36320056, 2022). "Recipient mice engrafted with primary leukemia cell expressing wild type BCR-FGFR1 were treated with FGFR1 and FLT3 inhibitor alone or in combination." (PMID 35906694, 2022). "Targeting BCL2 in the resistant cells leads to suppression of leukemia development in mouse models, which potentially provides an opportunity to treat patients that become resistant to FGFR1 inhibitors." (PMID 34734169, 2021).
leukemia (continued). "In summary, our studies showed that FGFR3 negatively regulates the generation of CD117+ leukemia stem-like cells by activating FGFR1-ERG-CD117 signaling." (PMID 33584313, 2020). "We found that FGFR3 deletion reprogrammed MA-AML cells into CD117+ leukemia stem-like cells by activating the FGFR1-ERG-CD117 signaling pathway." (PMID 33584313, 2020). "The results showed that the inhibition of FGFR1 and AKT, not ERK1/2, significantly reduced FGFR1 activation-induced ERG expression in 293T cells and leukemia cells, suggesting that FGFR1 upregulates ERG expression by activating PI3K/AKT signaling." (PMID 33584313, 2020). "Forced expression of the miR-17/92 cluster resulted in cell proliferation, while inhibition resulted in reduced cell growth and apoptosis, indicating that the miR-17/92 cluster is a downstream effector of FGFR1 in BCR-FGFR1 driven leukemia." (PMID 31105873, 2019). "Inhibition of FGFR1 can reverse this protective stroma-leukemia interaction and restore leukemia cell TKI sensitivity in the marrow niche." (PMID 30720426, 2019). "Several studies have demonstrated that increased FGFR1 activity, as a result of FGFR1 fusion kinases, drive leukemia/lymphoma development in mouse models." (PMID 27391347, 2016). "Conversely, FGF2 increased the proliferation of osteoblasts via FGFR1 IIIc, but its effects on osteoblast support of leukemia cell growth were limited." (PMID 27481339, 2016). "Xenografts of murine leukemia and lymphoma cell lines in mice have allowed evaluation of the ability of various FGFR1 inhibitors to suppress leukemia progression in vivo, but possibly do not represent the heterogeneity seen in primary human leukemias." (PMID 27391347, 2016). "Constitutive activation of FGFR1, through rearrangement with various dimerization domains, leads to atypical myeloproliferative disorders where, although T cell lymphoma are common, the BCR-FGFR1 chimeric kinase results in CML-like leukemia." (PMID 22701616, 2012). "Similarly, a case responding to ponatinib, another TKI inhibiting FGFR1, demonstrated a partial but significant response in leukemia with this translocation." (PMID 41180818, 2025). "Overall, the BCR::FGFR1 translocation is extremely rare, which prompted us to conduct a literature review upon diagnosis, revealing descriptions of rapidly progressive and challenging-to-treat leukemia." (PMID 41180818, 2025). "Mebendazole also led to prolonged survival in mice with FGFR1-dependent leukemia." (PMID 38835346, 2024). "Furthermore, as reported in a previous study, Rac1 activation promoted FGFR1-mediated leukemia occurrence in the stem cell leukemia syndrome, while Rac1 promoted HSPC expansion in initiating and maintaining leukemia in the mouse model." (PMID 36923939, 2023). "This superior survival further underscores the therapeutic importance of our original discovery of the leukemia promoting role by the non-classical truncated nuclear FGFR1 variant and provides a potentially improved treatment of all FGFR1 related leukemias." (PMID 35906694, 2022). "Targeting FGFR1 activation with a variety of drugs has proved effective in suppressing leukemia cell growth in vitro and leukemogenesis in mouse models of SCLL, as well as in SCLL patients and hence is potentially an effective way of treating this disease using targeted therapies." (PMID 35906694, 2022). "The results showed that PD17 and LY treatment, not PD98 treatment, significantly reduced the percentage of CD117-positive leukemia cells in MA-KO cells compared to MA-WT cells, suggesting FGFR1 may promote CD117-positive leukemia cells by AKT signaling." (PMID 33584313, 2020). "Additionally, we observed that that primary leukemia cells from Case 1 demonstrated sensitivity to the tyrosine kinase inhibitors ponatinib and dovitinib that can target FGFR1 kinase activity, whereas primary cells from Case 2 were resistant to both drugs." (PMID 31980503, 2020).
leukemia (continued). "In order to study whether FGFR1 signaling promotes the generation of CD117-positive leukemia cells, MA-WT and MA-KO cells were treated with FGFR1 inhibitor (PD173074, PD17), AKT inhibitor (LY294002, LY), and MEK inhibitor (PD98059, PD98), respectively." (PMID 33584313, 2020). "Our evidence, however, does suggest that the effectiveness of the treatment may depend on the myeloid or lymphoid lineage in the leukemia, and those with myeloid lineage leukemia may be more sensitive to FGFR1 TKI inhibition." (PMID 31980503, 2020). "The FGFR1 fusion proteins more frequently present in certain type of leukemia and lymphomas correlated with the 8p11 myeloproliferative syndrome are ZMYM2-FGFR1, Bcr-FGFR1, CEP110-FGFR1, FGFR1OP2-FGFR1, FOP-FGFR1 and CUX1-FGFR1, which are constitutively activated." (PMID 30423915, 2018). "Overall, based on the GI50, and cell growth inhibition as well as downstream molecular effects, BGJ398, AZD4547 and JNJ42756493 are relatively more effective and specific in targeting the FGFR1 signaling pathway in leukemia cell lines carrying FGFR1 fusion kinases." (PMID 27391347, 2016). "Unlike multikinase inhibitors, such as ponatinib, TKI258 and E3810, however, the BGJ398, JNJ42756493 and AZD4547 inhibitors appeared to specifically inhibit FGFR kinases and were shown to be very potent in suppressing growth in the FGFR1-dependent leukemia cells in our study." (PMID 27391347, 2016). "FOP-FGFR1, a fusion protein joining the N-terminus of FOP and kinase domain-containing C-terminus of FGFR1, causes myeloproliferative neoplasm (MPN), a form of leukemia." (PMID 23554904, 2013). "We now show that FGFR1 fusion kinase-mediated activation of IRAK1 in SCLL cells leads to increased accumulation of myeloid-derived suppressor cells (MDSCs) in vivo with a concomitant suppression of CD4/CD8 T-cells promoting an immune suppressive microenvironment leading to leukemia development." (PMID 34906138, 2021). "Noteworthy, FGFR1 can be activated via various ligands (FGF1-6, FGF-8, 19,21, and 23), and previous studies of leukemia and lymphoma cells show higher expression of FGF2 ligands." (PMID 37598282, 2023). "Cells transformed with tnFGFR1 are insensitive to FGFR1 inhibitors but treatment of these cells with the Quizartinib (AC220) FLT3 inhibitor, suppresses in vitro growth and development of leukemia in vivo." (PMID 35906694, 2022). "FGFR1 and 2, the receptor of FGF2, were differently expressed in leukaemia cells co-cultured with MSCs from different origin and FGFR2 expression was significantly increased in leukaemia cells co-cultured with MSCs from T-ALL mice after PCR validation." (PMID 36333298, 2022). "How FGFR1 is positioned in the exosome membrane (inside or out), how FGF2 binds FGFR1 in exosomes, and how exosomal FGF2 activates FGFR1 in leukemia cells, are areas of active investigation." (PMID 30720426, 2019). "In BBC2 and KG1 stem cell leukemia and lymphoma cells, the tumor suppressor miR-150-5p was downregulated by MYB and other factors [fibroblast growth factor receptor 1 (FGFR1) and MYC], but treatment with mebendazole showed increased antiproliferative activity and apoptosis induction." (PMID 38835346, 2024). "Considering the FGFR1 related leukemia are driven by both the full-length fusion kinase and the truncated tnFGFR1, we examined the long-term efficacy of the combination of FLT3 and FGFR1 inhibitors with our SCLL leukemia model." (PMID 35906694, 2022). "The Warburg effect occurs in leukemia with the help of enzymes such as pyruvate kinases M2 (PKM2), lactate dehydrogenase A (LDHA), pyruvate dehydrogenase kinase 1 (PDK1), and fibroblast growth factor receptor 1 (FGFR1)." (PMID 34659946, 2021). "In leukemia, PKM2, LDHA, PDK1, and FGFR1 play an important role in establishing the Warburg effect." (PMID 34659946, 2021).
leukemia (continued). "Treatment with BGJ398 significantly (P = 0.016) prolonged survival in the cohort of mice xenografted with leukemias over-expressing FGFR1, but not in the AML group showing low expression of FGFR1." (PMID 27391347, 2016). "To date, at least 11 FGFR1 fusion partners have been identified, most of which induce a myeloproliferative neoplasm or disorder (MPN/MPD) and lymphadenopathy, usually involving T-lymphoblastic lymphoma/leukemia predominantly of an immature T-cell type." (PMID 22701616, 2012). "TSLP may promote leukemia cell proliferation through several signaling pathways, including JAK-STAT, PI3K/mTOR, and MAPK, as well as through other factors such as RAS, IGF1R, and FGFR1." (PMID 40787610, 2025). "IRAK1 orchestrates a previously unknown FGFR1-directed immune escape mechanism in SCLL, through induction of MDSCs via regulation of IFN-γ signaling from leukemia cells, and targeting IRAK1 may provide a means of suppressing tumor growth in this syndrome by restoring immune surveillance." (PMID 34906138, 2021). "Taken together, these results suggest that some but not all BCR–FGFR1 fusion positive leukemias may respond to TKIs that target FGFR1 kinase activity." (PMID 31980503, 2020). "The FGFR1 transformation of hematopoietic stem cell models that we have developed have provided a unique opportunity to study the total cellular changes occurring in the microenvironment during leukemogenesis, which is not afforded by the analysis of human leukemias." (PMID 38730491, 2024). "Finally, the detection of both NUP214::ABL1 and PCM1::FGFR1 fusions in the near ETP-ALL of case 8 leaves no information as to which fusion was the primary and which was secondary in this leukemia." (PMID 38571499, 2024).
melanoma (44 papers, 2004 to 2025). A malignant, usually aggressive tumor composed of atypical, neoplastic melanocytes. "Subgroup analyses showed that the mutation frequencies of melanoma regarding FGFR1, FGFR2, FGFR3 and FGFR4 ranked 1st, 2nd, 2nd, and 2nd across all cancers, respectively." (PMID 36426352, 2022). "Pro252Arg/Ser/Thr somatic mutations in the fragment FGFR1 encoding its extracellular domain were identified among genetic drivers in human melanoma cell lines." (PMID 31167513, 2019). "FGFR1 has been listed among resistance-associated genes expressed transiently in melanoma cells." (PMID 31167513, 2019). "In melanoma cells, where baseline FGFR1 phosphorylation was low, the antibody exhibited limited antiproliferative effects." (PMID 40547805, 2025). "From the cytotoxicity assay, it is suggested that the dual inhibition of pan-Raf kinases and FGFR1 has a promising biological profile in treating melanoma." (PMID 39920399, 2025). "Patients with FGFR1-overexpressed melanoma were also found to have less response to pembrolizumab while FGFR-altered HCC tends to have progressive disease after immunotherapy." (PMID 38255923, 2024). "The expression of FGFR1 was documented in 67% of melanocytic nevi, with an observed increase up to 86% of primary melanomas." (PMID 38473753, 2024). "FGFR1 was highly expressed in a majority of melanoma cases, which created the signals in the tumor microenvironment to accelerate angiogenesis, cell growth, and therapeutic resistance." (PMID 37480145, 2023). "The therapeutic potentials of targeting CCHE1 and co-inhibiting FGFR1/LDHA in melanoma deserve more investigation by the in vivo studies." (PMID 37480145, 2023). "CCHE1 bound LDHA and modulated its activity in melanoma glycolysis via regulating FGFR1-mediated LDHA phosphorylation." (PMID 37480145, 2023). "CCHE1 promoted the glycolysis and proliferation of melanoma cells by enhancing FGFR1-mediated LDHA phosphorylation and activation." (PMID 37480145, 2023). "The melanoma additionally had mutations of TERT, DNMT3A, and PRSS3 and imbalanced chromosomal copy number gains in BRCA2, RET, FGFR1 (also referred to as FLT2), and IGF2." (PMID 35336833, 2022). "A nomogram, integrating clinicopathological variables including age, sex, ICIs categories, TMB, and FGFR1/2/3/4 status, was formulated to predict the 1-year OS, 3-year OS and 5-year OS of those ICIs-treated melanoma patients based on multivariable analysis." (PMID 36426352, 2022). "One notable member of this network is fibroblast growth factor receptor 1 (FGFR1), which was shown to be a key driver of melanoma angiogenesis and treatment resistance, common phenomena in Black individuals." (PMID 33983985, 2021). "In VGP primary melanomas, co-expression of FGF2 and FGFR1 is significantly associated with increased density of microvessels." (PMID 31167513, 2019). "Inhibition of FGF2 and FGFR1 in melanoma cells in vivo induced apoptosis and blocked intratumoral angiogenesis and tumor growth." (PMID 31167513, 2019). "Co-expression of the pair FGF2 and FGFR1 in melanoma was extensively characterized in the 1980s and 1990s." (PMID 31167513, 2019). "The existence of FGFR1 expression prior to BRAF inhibition allows the melanoma cells to react immediately on the drug-induced ligands without the need for selection." (PMID 30237393, 2018). "To further study the effect of Vegfr2 heterozygosity, alone or in combination with endothelial Fgfr1/2 inactivation in an independent tumorigenesis model, we tested B16 melanoma cell growth when transplanted into mice." (PMID 30283071, 2018). "Semiquantitative analysis of cDNA from melanoma cells and the fibroblast cell line MainUro revealed that FGFR1 is expressed in all analysed cell lines, while FGFR2-4 are expressed variably." (PMID 30237393, 2018). "Overall our data propose Ust and consequently 2-O sulfated CS/DS as a regulator of adhesion via the amount and activation of FgfR1 and the expression of Itga5 in melanoma cells." (PMID 28107390, 2017).